SLC16A14 (solute carrier family 16 member 14)
Description:
Proton-linked monocarboxylate transporter. May catalyze the transport of monocarboxylates across the plasma membrane.
Synonyms: MCT14; FLJ30794
Tractability: Antibody: UniProt places it where antibodies can reach, with medium confidence; UniProt predicts a signal peptide or a membrane-spanning region; its Gene Ontology location is reachable by antibodies, with medium confidence. PROTAC: ubiquitination databases record sites on it.
Gene: Protein-coding gene on chromosome 2 (230,034,974 to 230,068,999, reverse strand). Ensembl gene ENSG00000163053.
Subcellular location: Cell membrane
Subcellular location (Human Protein Atlas): Endoplasmic reticulum
Gene Ontology:
Molecular function: monocarboxylic acid transmembrane transporter activity; transmembrane transporter activity
Biological process: carboxylic acid transmembrane transport; monocarboxylic acid transport; transmembrane transport
Cellular component: plasma membrane
Genetic constraint (gnomAD): Loss-of-function variants: 16 observed, 40.86 expected, observed/expected ratio (o/e) 0.39, 90% interval 0.26 to 0.6. The upper end of that interval is the gene's LOEUF score, 0.6, which puts it in group 2 of 6, group 1 being the genes least tolerant of losing a copy. Missense variants: 533 observed, 681.43 expected, observed/expected ratio (o/e) 0.78, 90% interval 0.73 to 0.84. Synonymous variants: 248 observed, 271.98 expected, observed/expected ratio (o/e) 0.91, 90% interval 0.82 to 1.01.
Homologues: Orthologues: chimpanzee SLC16A14 (99% identical), macaque SLC16A14 (98% identical), mouse Slc16a14 (87% identical), pig SLC16A14 (87% identical), rat Slc16a14 (87% identical), guinea pig SLC16A14 (87% identical), rabbit SLC16A14 (83% identical), dog SLC16A14 (81% identical), tropical clawed frog slc16a14 (65% identical), Drosophila melanogaster CG13907 (30% identical), Drosophila melanogaster Mct1 (28% identical), Caenorhabditis elegans mct-6 (27% identical), and 10 more. Paralogues in human: SLC16A9 (29% identical), SLC16A12 (26% identical), SLC16A1 (25% identical), SLC16A7 (25% identical), SLC16A11 (24% identical), SLC16A3 (24% identical), SLC16A4 (23% identical), SLC16A6 (23% identical), SLC16A8 (23% identical), SLC16A5 (22% identical), SLC16A10 (22% identical), SLC16A13 (22% identical), and 1 more.
Diseases named in the same sentence as SLC16A14 in open-access papers:
SLC16A14 is named in the same sentence as 6 diseases in open-access papers, as found by Europe PMC text mining. Sharing a sentence is not in itself a finding about the gene and the disease. The quoted sentences say what the papers report.
breast carcinoma (2 papers, 2018 to 2022). "Notably, AFF3 expression was increased in luminal A and luminal B breast cancers, whereas SLC16A14 expression levels appeared unchanged." (PMID 30326937, 2018).
adenoma (1 paper, 2024). A neoplasm arising from the epithelium. "Some MP-RNAs interacted with much more partners in adenoma and cancer tissues than in paracancer tissues, such as SLC16A14, POLA2, PCDH11X, TASP1, TSPY20P." (PMID 38773399, 2024).
clear cell renal carcinoma (1 paper, 2014). A malignant epithelial neoplasm of the kidney characterized by the presence of lipid-containing clear cells within a vascular network. "The chimeras TRIP12->SLC16A14 and TFG->GPR128 have been found in cancer patients with clear cell renal carcinoma." (PMID 25133550, 2014).
ovarian carcinoma (1 paper, 2020). A malignant neoplasm originating from the surface ovarian epithelium. "However, higher expression of SLC16A14 was associated with longer progression-free survival of patients with ovarian cancer, and, conversely, was implicated in resistance to chemotherapy of ovarian cancer cell lines." (PMID 32584883, 2020).
cancer (5 papers, 2014 to 2024). A tumor composed of atypical neoplastic, often pleomorphic cells that invade other tissues. "Multiple cancer survival-related genes were found in these genes, including CDH17, PTPRJ, SLC16A14, TMTC2, and NOTCH4." (PMID 32426342, 2020). "However, studies on SLC16A4, SLC16A10, SLC16A11, SLC16A13, and SLC16A14 in cancer are still lacking." (PMID 34424811, 2021).
tumor (3 papers, 2017 to 2026). "At the single-cell level, SLC16A14 was mainly expressed in malignant cells, and communication analyses suggested that CALCR-related signaling may mediate tumor-endothelial interactions and contribute to an immune-excluded microenvironment." (PMID 42136962, 2026).